IL22 (interleukin 22)
Diseases named in the same sentence as IL22 in open-access papers (continued):
Sharing a sentence is not in itself a finding about the gene and the disease.
liver fibrosis (continued). "IL-22 levels also negatively correlate with the development of liver fibrosis." (PMID 36839448, 2023). "Furthermore, during the progression of hepatitis C to cirrhosis, the ratio of IL-22BP/IL-22 increases with the stage of liver fibrosis and peaks at the time of cirrhosis." (PMID 36839448, 2023). "Positive correlations between liver-infiltrating IL-22+ cells and liver fibrosis stage were identified, and blockade of IL-22 significantly reduces hepatic lymphocyte recruitment and fibrosis progression by relieving the expression of CXCL10 and CCL20 in HBV Tg mice." (PMID 34944732, 2021). "Furthermore, this study implied a protective role of IL-22 in this setting, as patients with high levels of this cytokine presented decreased hepatic fibrosis and portal hypertension." (PMID 33851257, 2021). "IL-22 can activate hepatic stellate cells (HSCs) by binding with IL-22R1, which can increase the synthesis of extracellular matrix (ECM) and aggravate HCV associated liver fibrosis." (PMID 34434945, 2021). "Thus, determining the source of IL-22 and the effect of other cytokines, such as IL-17, on IL-22 will help us better understand the role of IL-22 in liver fibrosis." (PMID 33869241, 2021). "Independent of its role during liver fibrosis, IL-22 possesses a rather pathogenic function during the development of HCC." (PMID 33851257, 2021). "IL-22 injection protects mice against BDL-induced liver fibrosis." (PMID 34211477, 2021). "Furthermore, this study observed that IL-22 actually enhanced liver fibrosis by inducing CCl4-mediated liver damage in IL-22RA1-deficient mice." (PMID 33851257, 2021). "In conclusion, the current data might encourage speculation that physiological levels of IL-22 enhance liver fibrosis, while overt IL-22 expression might induce more protective functions during fibrosis." (PMID 33851257, 2021). "However, caution is advised since IL-22 can also favor the development of HCC, a risk that is greatly increased for patients with liver fibrosis or cirrhosis anyhow." (PMID 33851257, 2021). "On one hand, increased expression of neutrophil (and mast cells)-derived IL-17 is a common signature of advanced liver fibrosis, which upregulates the expression of TGF-β receptor in HSCs and promotes liver fibrosis, and blocking IL-17/IL-22 alleviates liver fibrosis." (PMID 33763069, 2021). "Thus, more data are urgently needed to evaluate the therapeutic benefit of modifying the IL-22/IL-22BP axis in liver fibrosis and cirrhosis." (PMID 33851257, 2021). "In HBV- and HCV- infected patients, IL-22 was positively correlated with liver fibrosis stages." (PMID 33851257, 2021). "More studies are needed to shed light on the IL-22 function in liver fibrosis, but this cytokine may be considered a therapeutic opportunity for future clinical management of liver disease." (PMID 29892294, 2018). "Therefore, further in vivo studies using several models of liver fibrosis are required to illustrate the precise role of IL-22 in the pathogenesis of liver fibrosis." (PMID 27681697, 2016). "Both IL-22 and miRNA-200a alleviate the pathogenesis of liver fibrosis." (PMID 27819314, 2016). "Moreover, our study also showed that treatment with IL-22 accelerated the resolution of liver fibrosis in mice." (PMID 27819314, 2016). "So, the protective role of IL-22 against hepatic fibrosis induced by schistosome may involve the same mechanism." (PMID 28050571, 2016). "The most studied members of the IL-10 family related to liver fibrosis are IL-10, IL-20, and IL-22." (PMID 26199463, 2015). "Overexpression of IL-22 or recombinant IL-22 treatment decreased the expression of alpha-smooth muscle actin (αSMA) in cultured hepatic stellate cells and also in the fibrotic liver of the mice with CCl4-induced liver fibrosis." (PMID 26199463, 2015). "Furthermore, an inverse correlation between the degree of liver fibrosis and IL-22 concentration was recently detected in the liver tissues of patients with chronic HBV infection." (PMID 24799907, 2014).
liver fibrosis (continued). "IL-22 may thus act as a regulatory cytokine counteracting liver fibrosis during schistosomiasis." (PMID 40446079, 2025). "However, IL-22 has also been reported to exert pro-liver fibrosis effects." (PMID 39995661, 2025). "Moreover, treatment with IL-22 accelerated the resolution of liver fibrosis in mice." (PMID 40607394, 2025). "In addition, IL-22 and IL-23 seem to decrease liver fibrosis." (PMID 38069218, 2023). "However, the role of Th22 cells and IL-22 in liver fibrosis remains controversial." (PMID 33869241, 2021). "The interactions between IL-22 and IL-17 secreted by infiltrating Th cells may contribute to the pathological development of NAFLD, and IL-22 signaling is also suggested to be associated with liver fibrosis." (PMID 34944732, 2021). "However, in the presence of IL-17, IL-22 recruits Th17 to aggravate liver fibrosis." (PMID 33869241, 2021). "The Bin Gao groups revealed that overexpression of IL-22 by either gene targeting (e.g., IL-22 transgenic mice) or exogenous administration of adenovirus-expressing-IL-22 (Ad-IL-22) could reduce liver fibrosis and accelerate the resolution of CCl4-induced liver fibrosis during recovery." (PMID 24623532, 2014). "IL-22 activated the STAT3 signaling pathway by binding to its receptor, which in turn induced senescence in HSCs and attenuated liver fibrosis." (PMID 39995661, 2025). "In a CCl4-induced mouse model of liver fibrosis, ASP promoted IL-22 secretion, inhibited HSCs activation, and effectively attenuates fibrosis through the IL-22/STAT3 pathway." (PMID 39995661, 2025). "Using the CDAHFD diet-based model, where animals develop fatty livers with fibrosis, IL-22-ScFv reduced NAS scores and hepatic fibrosis, accompanied by decline in gene expression of key fibrosis genes." (PMID 38811532, 2024). "In HBV-transgenic mice, the blockade of IL-22 attenuates the levels of CCL20 and CXCL10 in the liver and reduces Th17 recruitment to inhibit liver fibrosis." (PMID 37041599, 2023). "IL-22 signals through IL-22Rα and IL-10Rβ, triggering STAT3 signaling and has been reported to promote liver regeneration and to decrease liver fibrosis and injury." (PMID 33824326, 2021). "Similar to the results of expression of miR-200a, we found that the liver fibrosis recovery slower after miR-200a inhibitor injection compared with PBS group and the IL-22 + miR-200a inhibitor group according to the Ishak fibrosis score." (PMID 27819314, 2016). "The interaction between IL-22/STAT3 and Wnt/β-catenin pathway is involved in the development of hepatic fibrosis in vivo." (PMID 27819314, 2016). "In conclusion, our results demonstrate that IL-22/STAT3 regulates HSC activation and ameliorates liver fibrosis through modulating expression of miR-200a and β-catenin." (PMID 27819314, 2016). "We further examined the regulatory role of IL-22 in the expression of miR-200a and its target in a HSC cell line, primary HSCs and a rat model of liver fibrosis." (PMID 27819314, 2016). "Additionally, an inverse correlation between the degree of liver fibrosis and IL-22 concentration was recently observed in the liver tissues of patients with chronic HBV infection, hypothesizing that IL-22 may also play an antifibrotic role in human liver diseases." (PMID 24799907, 2014). "As a result, several other cytokines, such as TGF-β, IL-22, IL-10, and IL-6, which are known to play important roles in liver fibrosis, were not covered, as they were not addressed in the eligible studies." (PMID 40362271, 2025). "This fibrogenic effect was confirmed in the chronic CCl4 model, where mice lacking IL-22 signaling (Il22ra1-/-) exhibited reduced hepatic fibrosis compared to their wild-type counterparts." (PMID 39156888, 2024). "Consistently, IL-22 and IL-22(+) cells are significantly increased in the peripheral blood of HCV patients, while the number of IL-22(+) cells in the liver is positively correlated with the liver fibrosis score." (PMID 33869241, 2021).
liver fibrosis (continued). "Moreover, administration of IL-22 inhibits HSC activation, reduces the production of pro-inflammatory factors (IL-1β, IL-6, and TNF-α), and ameliorates liver fibrosis in CCl4-induced liver fibrosis." (PMID 33869241, 2021). "Additionally, in vivo injection of IL-22 in BDL mice reduces collagen α1 (I) and α-SMA production to alleviate liver fibrosis." (PMID 33869241, 2021). "Type 3 inflammation, characterized by a polarization towards a Th17 response and the production of IL-17A, IL-17F, IL-22 and IL-26 by Th17 cells, Th 22 cells, neutrophils and mast cells has been identified as a driver of chronical liver injury and of TGF-β-dependent liver fibrosis." (PMID 33036244, 2020). "We further identified the inverse association between expression of STAT3 and β-catenin in HSC, indicating there may have a cross-talk between IL-22/STAT3 and Wnt/β-catenin signaling pathways in development of liver fibrosis." (PMID 27819314, 2016). "We concluded that IL-22 inhibits HSC activation and ameliorates liver fibrosis through enhancing expression of miR-200a and reducing expression of β-catenin, suggesting there may be a crosstalk between IL-22/STAT3 and β-catenin pathway." (PMID 27819314, 2016). "Interestingly, our results have shown significantly lower serum concentrations of IL-22 in patients with steatosis, particularly in those with advanced liver fibrosis, as well as a negative correlation between CAP and serum levels of IL-22." (PMID 39200991, 2024). "These elevated IL-22 levels during CHB and CHC infections could contribute to chronic inflammation and increased severity of liver fibrosis, by enhancing the recruitment of proinflammatory Th17 cells into the liver and a persistent activation and proliferation of HSCs." (PMID 39156888, 2024). "Furthermore, IL-22 induces the proliferation of HSCs, and the Th22 cell level is positively related to the progression of CHC to cirrhosis, suggesting that Th22/IL-22 facilitates HCV-related liver fibrosis." (PMID 36839448, 2023).
influenza infection (46 papers, 2012 to 2025). "IL-22 has been demonstrated to promote airway epithelial repair in vivo, with IL-22-deficient mice having reduced epithelial proliferation and exacerbated collagen deposition and morbidity in the context of influenza infection." (PMID 33562816, 2021). "Increased levels of bioactive IL-22 in IL-22BP-deficient mice lead to reduced inflammation and increased tight junctions in their lungs, which protect the mice from influenza infection." (PMID 34868019, 2021). "Failure to induce expression of IL22 following influenza infection was associated with inefficient activation of AhR." (PMID 34906172, 2021). "Moreover, IL-22 is essential to allow alveolar repair following Influenza pneumonia, while elevated IL-22BP expression increases the risk of severe pulmonary infections." (PMID 37753072, 2023). "Together, these results suggest an association between suppressed IL22 expression and altered AhR activation and indicate that failure of AhR activation may have led to suppressed IL22 expression following influenza infection." (PMID 34906172, 2021). "For example, it has been shown that IL-22−/− mice previously infected with influenza are more susceptible to a secondary bacterial infection with S. pneumoniae and exhibit decreased survival and increased bacterial burdens when compared to wild-type coinfected animals." (PMID 29988424, 2018). "We next analyzed the production of IL-22 in the BAL as this cytokine is known to be produced in the lungs during influenza infection." (PMID 40612502, 2025). "This inadequacy in maintaining IL-22 levels was proposed as a catalyst for aberrant epithelial repair and compromised immune responses, potentially escalating flu severity." (PMID 40291836, 2025). "Mice super-infected with influenza and A. fumigatus had a decreased expression of IL-17, IL-22, and IL-23 compared to those infected with A. fumigatus alone." (PMID 39949778, 2025). "IL-22 is protective during influenza infection by improving the tight junction formation and decreasing lung inflammation." (PMID 38101567, 2024). "Striking reactivities were observed particularly for IFN-α8, IFN-γ, IL-6, IL-7, IL-12p70, and IL-22, while serum from 1 patient with influenza showed high MFI levels for both GM-CSF and soluble RANK ligand." (PMID 36752204, 2023). "In a mouse model of secondary bacterial pneumonia after severe influenza infection, the presence of IL-22 reduced the inflammatory response, preserved epithelial barrier function, decreased the bacterial burden, and improved survival." (PMID 37207185, 2023). "Since IL-22 can be blocked by IL-22BP, IL-22BP inhibitors have been assumed to be effective at improving influenza prognosis." (PMID 36839448, 2023). "al. showed that iNKT cells limit influenza pathology in a preclinical mouse model through the production of IL-22." (PMID 35313965, 2022). "For instance, Th17 cell effector cytokines (IL-1β, IL-17A, and IL-22) are upregulated in the plasma of patients with laboratory-confirmed A (H3N2) influenza and/or HPIV infections." (PMID 34602860, 2021). "In this study, we determined the effects of PM exposure on IL22 responses following influenza infection." (PMID 34906172, 2021). "As observed in the inflamed GI tract, IL-22 levels increase and IL-22BP levels decrease in the lung during influenza infection, making the lung a more pro-IL-22 environment." (PMID 34868019, 2021). "Paradoxically, this latter paper further demonstrated that IL22 was important in protecting against pulmonary inflammation during sublethal influenza infection and that it was critical in providing resistance to secondary bacterial infections." (PMID 34906172, 2021). "Collectively the findings from our animal studies demonstrate that early life exposure to PM results in the inability to induce IL22 activation upon Flu infection resulting in enhanced lung injury and Flu morbidity and mortality." (PMID 34906172, 2021).
influenza infection (continued). "Conventional NK cells were found to be the predominant source of IL-22 during influenza infection, with adoptive transfer of IL-22 sufficient NK cells into IL-22 deficient mice able to partly rescue the impaired epithelial healing seen in these mice." (PMID 33562816, 2021). "We determined the expression of IL22 at different times following PM exposure and influenza infection in lungs." (PMID 34906172, 2021). "During severe influenza, IL-22 immunotherapy can enhance the integrity of lung tissue and reduce the systemic invasion of secondary bacteria." (PMID 34692846, 2021). "IL-22 is required for normal repair of the injured lung after influenza infection and mice treated with IL-22 show decreased inflammation and lung leak." (PMID 34597299, 2021). "Our findings are consistent with previous studies that have showed decreased total cell counts, neutrophils, lymphocytes, and macrophages in the BAL of mice on a pro-IL-22 genetic setting after influenza injury." (PMID 34597299, 2021). "Supporting this was the finding that addition of exogenous IL-22 in a murine model of influenza infection limited tissue damage." (PMID 33968082, 2021). "The protective role of IL22 during fungal and bacterial infection is well documented; however, there are controversial reports on the importance of IL22 functions in influenza infection." (PMID 34906172, 2021). "The vehicle-exposed influenza infected mice showed a significant increase in IL22 expression as compared to vehicle-exposed sham infected mice." (PMID 34906172, 2021). "Together, these data indicate that restoration of lung microbial metabolites provides resistance to PM-exacerbated influenza infection by increasing IL22 expression." (PMID 34906172, 2021). "Our group’s previous work showed that IL-22 results in less protein leak into the lung after influenza injury due to promotion of tight junction formation in the epithelial layers of the lung." (PMID 34597299, 2021). "In the current study, we report the effects of PM exposure on lung IL22 levels and the lung microbiome, which contribute to an increased severity of influenza infection in infant mice." (PMID 34906172, 2021). "IL-22–/– mice were shown to have increased bacterial burden and mortality compared with WT mice in a model of influenza, S. pneumoniae super-infection." (PMID 32582219, 2020). "In that study, IL-22–/– mice had increased lung injury, decreased lung function, and increased pulmonary fibrosis compared with WT mice 3 weeks following influenza infection." (PMID 32582219, 2020). "IL-22 is a tissue-regenerative cytokine secreted by NK cells and Th17 cells in the lung, trachea and airways during influenza infection." (PMID 32974217, 2020). "Conventional natural killer cells were shown to be a primary source of IL-22 following influenza challenge in mice." (PMID 32582219, 2020). "IL-22 enhances airway barrier function, improving the outcome of S. aureus superinfection of the lung after influenza." (PMID 32637365, 2020). "The degree of similarity between SARS-CoV2 and influenza pathogenesis is currently unclear; however, it is likely that IL-22 plays a role in epithelial barrier integrity." (PMID 32582219, 2020). "IL-22 is produced during influenza by pulmonary NK cells and RORγ+ αβ, and γδ T cells and binds IL-22Rα1 on AECs and endothelial cells, an interaction that can be antagonized by its soluble form, IL-22BP." (PMID 32117216, 2020). "This has led to a number of studies establishing a role for IL-22 in maintaining epithelial barrier integrity in the context of influenza infection." (PMID 32637365, 2020). "Shortly thereafter, influenza infection was shown to induce IL-22 production by invariant natural killer T (iNKT) cells in the lung." (PMID 32582219, 2020). "Particular interest has been shown in the impact of influenza and super-infection with either S. aureus or S. pneumoniae on the effects of IL-22." (PMID 33003458, 2020).